ANO2 (anoctamin 2)
Description:
Calcium-activated chloride channel (CaCC) which may play a role in olfactory signal transduction. Odorant molecules bind to odor-sensing receptors (OSRs), leading to an increase in calcium entry that activates CaCC current which amplifies the depolarization of the OSR cells, ANO2 seems to be the underlying chloride channel involved in this process. May mediate light perception amplification in retina.
Synonyms: C12orf3; TMEM16B
Tractability: Antibody: UniProt places it where antibodies can reach, with high confidence; its Gene Ontology location is reachable by antibodies, with high confidence; UniProt predicts a signal peptide or a membrane-spanning region; the Human Protein Atlas places it where antibodies can reach. PROTAC: ubiquitination databases record sites on it; a small molecule that binds it is known.
Target class: Ion channel; Chloride channel; Other ion channel; Calcium-activated chloride channel
Gene: Protein-coding gene on chromosome 12 (5,531,869 to 5,946,232, reverse strand). Ensembl gene ENSG00000047617.
Subcellular location: Cell membrane
Subcellular location (Human Protein Atlas): Plasma membrane; Nucleoplasm
Pathways (Reactome):
Disease: Induction of Cell-Cell Fusion
Sensory Perception: Olfactory Signaling Pathway
Transport of small molecules: Stimuli-sensing channels
Gene Ontology:
Molecular function: intracellularly calcium-gated chloride channel activity; protein binding; protein dimerization activity; chloride channel activity
Biological process: chloride transmembrane transport; monoatomic ion transmembrane transport
Cellular component: plasma membrane
Genetic constraint (gnomAD): Loss-of-function variants: 104 observed, 119.79 expected, observed/expected ratio (o/e) 0.87, 90% interval 0.74 to 1.02. The upper end of that interval is the gene's LOEUF score, 1.02, which puts it in group 4 of 6, group 1 being the genes least tolerant of losing a copy. Missense variants: 1,265 observed, 1,255.7 expected, observed/expected ratio (o/e) 1.01, 90% interval 0.96 to 1.05. Synonymous variants: 482 observed, 473.63 expected, observed/expected ratio (o/e) 1.02, 90% interval 0.94 to 1.1.
Homologues: Orthologues: chimpanzee ANO2 (98% identical), dog ANO2 (92% identical), mouse Ano2 (92% identical), rat Ano2 (92% identical), guinea pig ANO2 (92% identical), pig ANO2 (91% identical), tropical clawed frog ano2 (68% identical), zebrafish ano2b (59% identical), zebrafish ano2a (29% identical). Paralogues in human: ANO1 (56% identical), ANO3 (37% identical), ANO4 (37% identical), ANO5 (35% identical), ANO6 (32% identical), ANO7 (32% identical), ANO9 (27% identical), ANO8 (19% identical), ANO10 (17% identical), PPP1R7 (8% identical).
Diseases named in the same sentence as ANO2 in open-access papers:
ANO2 is named in the same sentence as 22 diseases in open-access papers, as found by Europe PMC text mining. Sharing a sentence is not in itself a finding about the gene and the disease. The quoted sentences say what the papers report.
multiple sclerosis (5 papers, 2016 to 2024). A progressive autoimmune disorder affecting the central nervous system resulting in demyelination. "Gene NPSR1 promotes the malignant phenotype of adenocarcinoma of the lung and thyroid cancer cells, and Ano2 is associated with multiple sclerosis." (PMID 38891594, 2024). "We identified six multiple sclerosis patients with antibodies against the flotillin-1/2 complex (2.1%) and one multiple sclerosis patient with antibodies against anoctamin-2 (0.35%)." (PMID 37091585, 2023). "Our study aims to analyse the frequency and clinical relevance of antibodies against neurofascin-155, anoctamin-2 and flotillin-1/2 complex in multiple sclerosis." (PMID 37091585, 2023). "Although the search for autoantigen in patients with multiple sclerosis has been ongoing for decades and several proteins have been postulated to be potent autoantigens, such as α B-crystallin, anoctamin 2, and KIR4.1, the exact target autoantigen of MS remains unclear." (PMID 28070525, 2016). "In our association analysis, we allowed the seropositivity cutoff to vary within a given range of possible values, similarly done in a recent study of molecular mimicry between Anoctamin 2 and EBNA1 in multiple sclerosis." (PMID 34291062, 2021).
Anxiety (2 papers, 2019 to 2021). Intense feelings of nervousness, tension, or panic often arise in response to interpersonal stresses. "In this study, we report that loss of TMEM16B (Ano2) function leads to behavioral abnormalities, including impaired anxiety-related behaviors and context-independent auditory fear expression." (PMID 31482844, 2019). "Collectively, all these three different assays indicate that Ano2 KO mice are deficient in anxiety-related behaviors." (PMID 31482844, 2019). "It would be of interest to conduct a more targeted knockout approach and test how removal Ano2 from SOM+ neurons of CeL affects anxiety-related behaviors." (PMID 31482844, 2019). "This scenario is in accordance with the reduced auditory fear expression and anxiety-like behaviors of Ano2 KO mice." (PMID 31482844, 2019). "Here we report that Ano2 knockout mice exhibit impaired anxiety-related behaviors and context-independent fear memory, thus implicating TMEM16B in anxiety modulation." (PMID 31482844, 2019). "Our finding that Ano2 knockout mice exhibit impaired anxiety-related behaviors and fear memory indicates that the physiological function of TMEM16B is important for the processing and expression of anxiety." (PMID 31482844, 2019). "Given that anxiety and fear conditioning involves multiple brain regions including amygdala and hippocampus, it is important to examine Ano2 expression and physiological function in amygdala to assess the potential relevance to anxiety." (PMID 31482844, 2019). "To further examine anxiety-related behaviors of Ano2 KO mice, we tested for their performance in the elevated plus maze (EPM)." (PMID 31482844, 2019). "To look into the physiological relevance of TMEM16B in anxiety, we performed a battery of anxiety-related behavior tests of 3–4 months old Ano2 knockout (KO) mice that have sequences for farnesylated mCherry inserted into the coding sequence for Ano2, and used their wildtype littermates as controls." (PMID 31482844, 2019). "This alteration in neuronal signaling may alter the inhibitory tone in the central amygdala (CeA), thereby affecting disinhibition of CeA output neurons that are involved in anxiety and conditioned fear memory in Ano2 KO mice." (PMID 31482844, 2019). "Our finding that Ano2 KO mice displayed impaired auditory fear expression, raises the intriguing possibility that TMEM16B expressing neurons in the amygdala contribute to the regulation of fear and anxiety-related behaviors." (PMID 31482844, 2019). "Increased inhibition of SOM+ CeL neurons in Ano2 KO mice could reduce the extent of their excitation by BLA neurons as well as their ability to inhibit downstream neurons in PAG, thus resulting in a reduction of fear and anxiety-related behaviors." (PMID 31482844, 2019). "Ano2 mRNA expression is enriched in brain regions including the amygdala, lateral septum, and hippocampus according to the Allen Brain Atlas, raising the intriguing question regarding the role of the TMEM16B Ca2+-activated Cl- channel in anxiety-related behaivor." (PMID 31482844, 2019). "Thus, Ano2 KO mice display enhanced PPI and reduced anxiety-related behavior." (PMID 31482844, 2019).
Autoimmunity (2 papers, 2019 to 2024). The occurrence of an immune reaction against the organism's own cells or tissues. "A blood brain barrier phenotype is present as well as autoimmunity and autophagy with ANO2, HLA-DQB1, MTMR3, and SEC16A." (PMID 31026304, 2019).
panic disorder (2 papers, 2014 to 2019). An anxiety disorder characterized by multiple unexpected panic attacks with persistent concern of recurring attacks. "ANO2 and ANO6 are associated with panic disorder and major depressive disorder, respectively." (PMID 24473445, 2014).
bleeding disorder (1 paper, 2016). "ANO2 is involved in olfaction, whereas ANO6 works as a scramblase whose mutation causes a rare bleeding disorder, the Scott syndrome." (PMID 26811235, 2016).
medulloblastoma (1 paper, 2025). A malignant, invasive embryonal neoplasm arising from the cerebellum. "Through repositioning via a nuclear receptor, estradiol was found to interact with the ion channel target ANO2 (Q9NQ90), which is associated with indications such as shingles and medulloblastoma." (PMID 39860130, 2025).
Obesity (1 paper, 2019). Accumulation of substantial excess body fat. "Until now, the specific roles of ANO2, CAMK2D, SLC8A1, PDE2A, CALML3, GNG7, and CALML6 genes in olfactory-related dietary patterns and obesity in humans have not been apparently explored; therefore, further investigation in these research areas is warranted." (PMID 31057674, 2019).
Opportunistic infection (1 paper, 2017). An infection that is caused by a pathogen that would generally not be able to cause an infection in a host with a normal immune system. "Serratia marcescens ano1 and ano2 had predicted virulence factors possibly involved in attacking parasites and/or causing opportunistic infection in mosquito hosts." (PMID 28861046, 2017).
ANO2 also shares sentences with these, for which no sentence is quoted: cancer (2 papers); thyroid cancer (2); adenocarcinoma of the lung (1); Anosmia (1); anxiety disorder (1); Crohn disease (1); cystic fibrosis (1); endometriosis (1); major depressive disorder (1); post-traumatic stress disorder (1); Scott syndrome (1); Tremor (1); tumor (1); Von Willebrand disease (1).